EMP3 (epithelial membrane protein 3 (MAM blood group))
Diseases named in the same sentence as EMP3 in open-access papers (continued):
Sharing a sentence is not in itself a finding about the gene and the disease.
tumor (continued). "Here, we elucidated the tumor progressive effects of EMP3 through PI3K/Akt pathway and uPA/MMP-9 cascade in HCC cells." (PMID 26472188, 2015). "A positive correlation between EMP3 protein expression as detected by either IHC or WB analysis was found on 43 tumor samples, with statistical significance (P = 0.0038)." (PMID 24083241, 2013). "EMP3 was expressed in the cytoplasm and in the cell membrane of tumor cells, as well as in lymphocytes, macrophages, endothelial cells, and perivascular infiltrates." (PMID 24083241, 2013). "In contrast, the frequency of the EMP3 promoter hypermethylation is inversely correlated with the histologic tumor grade, with statistical significance." (PMID 24083241, 2013). "Similarly, EMP3 exhibited higher expression in the Tumor group compared to the Normal group, but the difference was not statistically significant (p > 0.05)." (PMID 39866225, 2025). "Additionally, genes like COL4A1, PLOD2, and PXDN, which participate in extracellular matrix remodeling, alongside immune-related genes such as CYFIP2, EMP3, and HLA-B, are instrumental in modulating the tumor microenvironment and facilitating immune evasion." (PMID 39949776, 2025). "In addition, silencing EMP3 at 72-96 h significantly reduced the number of tumor cells that migrated (p < 0.01)." (PMID 38229014, 2024). "Mechanistically, EMP3 enhances the malignant potential of tumor cells by promoting EMT." (PMID 38229014, 2024). "This rich dataset provides a wealth of testable hypotheses for future mechanistic investigations on both tumor-intrinsic and tumor-extrinsic effects of EMP3." (PMID 37936247, 2023). "In conclusion, this study identifies novel interacting partners of EMP3, thereby highlighting its multi-localizing nature while clarifying the subcellular context in which it could operate as a tumor-promoting protein." (PMID 37936247, 2023). "Consequently, EMP3’s stabilizing effect provides an additional layer of tumor cell resistance against targeted kinase inhibition." (PMID 37936247, 2023). "In GBM with high CD44 expression, EMP3 is frequently up-regulated and might be a vital role in tumor initiation and advancement in primary GBM." (PMID 36217151, 2022). "Furthermore, EMP3 suppressed T cell infiltration into GBM tumours by inhibiting the secretion of CXCL9 and CXCL10 by macrophages and led to an effective response to anti-PD1 therapy." (PMID 33964937, 2021). "Moreover, we observed that EMP3 affected macrophages, causing inhibition of antitumour immunity via suppression of CD4+ and CD8+ T cell infiltration into GBM tumours and downregulation of CXCL9 and CXCL10 production by macrophages." (PMID 33964937, 2021). "Notably, the proportions of tumor‐infiltrating immune cells showed significant differences between the high and low EMP3 subsets." (PMID 34268874, 2021). "In addition, as expected, in comparison with adjacent tissues, a significant increase in EMP3 was revealed in the tumor core region." (PMID 34268874, 2021). "Moving forward, it will be interesting to explore whether EMP3-high macrophages in the GBM immune microenvironment are able to inhibit tumor-infiltrating CTLs via a similar mechanism." (PMID 34067658, 2021). "However, knockout of EMP3 combined with anti-PD1 therapy resulted in an improvement in tumour growth delay." (PMID 33964937, 2021). "We found that PD-L1 was decreased in EMP3_KO tumours, indicating that EMP3 could induce the immunosuppressive ligand PD-L1 in GBM." (PMID 33964937, 2021). "Although EMP3 was considered as a positive force on the activation of the PI3K/AKT pathway in tumor cells [20.26], investigations on EMP3 and CDDP-resistant GC, as well as the key mechanisms of which EMP3 enhanced the activity of the PI3K/AKT pathway in GC cells are limited." (PMID 31895687, 2019).
tumor (continued). "EMP3, was previously reported to be a tumor suppressor gene for several solid tumors, and is drawing attention as a novel prognostic marker, since its expression level or hypermethylation of the promoter region is associated with clinical prognosis in these cancer types." (PMID 27527869, 2017). "Cooperation among EMP3 and these membrane receptors may allow integrated intracellular signaling that modulates tumor growth and invasion." (PMID 27527869, 2017). "The EMP3 hypermethylation is demonstrated by the immunonegative staining of tumor cells." (PMID 24083241, 2013). "Likewise, it will be relevant to investigate how EMP3 in T cells impacts anti-tumor immunity." (PMID 34067658, 2021). "In a study of EMP3, researchers found that EMP3 inhibits T-cell infiltration in GBM and promotes tumor progression." (PMID 38862250, 2024). "Overall, an inverse correlation was noted between tumor purity and the expression levels of IGF2BP3, EMP3, TUBA1C, AK2 and IGFBP2 (average PCC = −0.48)." (PMID 38171932, 2023). "EMP 1 is involved in tumor cell adhesion through the PI3K/AKT pathway, EMP 2 contributes to tumor cell migration via the FAK/Src pathway, and EMP 3 plays a role in tumor cell survival and metastasis through the ErbB2-PI3K-AKT pathway." (PMID 37629198, 2023). "Using bioinformatics tools and available databases, they demonstrated that EMP3 and TIMP1 are overexpressed in tumor tissue than in control normal brain tissue and that increased expression of these genes is associated with poorer prognosis for patients." (PMID 35454784, 2022). "EMP3 is thus a critical immunosuppressive factor for recruiting TAMs in GBM and suppressing intratumoural T cell infiltration to facilitate tumour progression and is a potential therapeutic target." (PMID 33964937, 2021). "However, the role of EMP3 in the tumor immune microenvironment remains unclear." (PMID 34268874, 2021). "And IGFBP2, EMP3, TIMP1 and SERPINE1 are all highly expressed in LGG tumor tissues compared with normal brain tissues." (PMID 32328202, 2020). "EMP3 belongs to the PMP-22/EMP/MP20 family, which is thought to be involved in cell proliferation, cell-cell interactions and function as a tumor suppressor." (PMID 33123464, 2020). "Overexpression of EMP3 in macrophages inhibits CD8+ cytotoxic T lymphocytes (CTLs), which are involved in tumor progression, viral infection, and type IV allergy." (PMID 31652725, 2019). "The roles of EMP3 in activation of PI3K by ErbB2-ErbB3 and in tumor promotion by P2X7R need to be further explored." (PMID 26472188, 2015). "In GBM, there is frequent hypermethylation of tumour suppressors (RB1, EMP3, RASSF1A and BLU), cell cycle regulators (p16INK4a and p15INK4b), DNA repair genes (MGMT, MLH1), and genes involved in tumour invasion and apoptosis (DAPK, TIMP3 and CDH1)." (PMID 22771539, 2013). "EMP3 exhibited high expression in some tumor and normal tissues, while also showing low or no expression in other tumor and normal liver tissues." (PMID 39866225, 2025). "The expression of EMP3, GSAP, SLC2A10, and SWAP70 was higher in tumor periphery." (PMID 36727078, 2022). "We found that EMP3 expression correlated with the expression of M2 TAM markers in both the TCGA and CGGA datasets and that EMP3 was correlated with immunosuppressive factors of tumour cells and factors of exhausted cytotoxic T lymphocytes." (PMID 33964937, 2021). "Regardless, EMP3-dependent activation of TGF-β signaling appears to be pathologically relevant, because EMP3-depleted intracranial GBM xenografts were shown to exhibit reduced tumor growth along with decreased p-Smad 2/3 levels." (PMID 34067658, 2021). "Furthermore, clarification of the composition and role of the EMP3:CD44 complex in other cells and tissues offers an approach to understanding and manipulating the tumour suppressor and oncogenic properties of EMP3 in diverse cancers." (PMID 32678083, 2020).
tumor (continued). "EMP3 expression was found to be correlated with the activation of TGF-β/Smad2/3 signaling by interaction with TGFBR2, which resulted in TGF-β stimulated gene expression and tumor cell proliferation." (PMID 32857809, 2020). "In addition, we observed the correlated EMP3 and CD44 staining positivity in paraffin-embedded archival tumor specimens (n = 60, Spearman correlation r = 0.780, P < 0.0001." (PMID 27527869, 2017). "In conclusion, our findings revealed that EMP3 might be a potential target for CD44-high GBMs and highlight the essential functions of EMP3 in TGF-β/Smad2/3 signaling activation and tumor progression." (PMID 27527869, 2017). "Our study reveals that EMP3 contributes to tumor aggressiveness by MMP-9 and uPA, but not MMP2, on the PI3K/AKT pathway in HCC cells." (PMID 26472188, 2015). "In contrast, other reports do not support EMP3 as a candidate of tumor suppressor gene and suggest its function in tumor aggressiveness." (PMID 26472188, 2015). "Epithelial membrane protein-3 (EMP3), a typical member of the epithelial membrane protein (EMP) family, is epigenetically silenced in some cancer types, and has been proposed to be a tumor suppressor gene." (PMID 26472188, 2015). "Expression data of EMP1, EMP2, EMP3 and PMP22 were obtained from all tumor samples." (PMID 21159173, 2010). "However, combining CDK2 inhibition with EMP3 silencing sufficiently compromises the viability of NCH1425 GSCs, highlighting how multiple insults may be required to target stem-like tumor cells." (PMID 37936247, 2023). "However, we did not observe the same positive correlation between EMP3 expression and CDK2 protein levels, and this may be due to the confounding effect of other upstream regulators of CDK2 activity in bulk tumor samples." (PMID 37936247, 2023). "Notably, we observed that patients with high EMP3 expression also had high expression of the immune checkpoints PD1/PDL1 and CTLA4, which may explain why immune activation was enriched in the EMP3 high subgroup, but did not hinder tumor progression." (PMID 34268874, 2021).
cancer (24 papers, 2010 to 2024). A tumor composed of atypical neoplastic, often pleomorphic cells that invade other tissues. "Herein, we mainly summarized the structure, mutation, and modification sites of PMP22, EMP1, EMP2, and EMP3, as well as the diseases related to these proteins, especially cancer types." (PMID 36217151, 2022). "In this context, we highlight in this review the functional aspects of the EMP family members EMP1, EMP2, and EMP3 related to their pathophysiology, particularly where associated with cancer metastasis." (PMID 31652725, 2019). "EMP3 knockout can promote the proliferation of cancer cells, while overexpression impairs the migration ability of cells and promotes apoptosis." (PMID 36217151, 2022). "On the other hand, the epithelial membrane protein 3 (EMP3) is a peripheral myelin protein whose overexpression can increase the invasive ability of cancer cells." (PMID 32503307, 2020). "EMP3 over-expression promoted cancer cell proliferation and migration through activating ErbB2-PI3K-AKT pathway in patients with upper urinary tract urothelial carcinoma." (PMID 27527869, 2017). "Epithelial membrane protein 3 (EMP3) can affect the PI3K-Akt pathway in cancer cells." (PMID 39062573, 2024). "Increasing evidence suggests that EMP3 might be a driving force in tumorigenesis and the progression of certain cancers." (PMID 38229014, 2024). "Considering the role of glycosylation in cancer, it will be important to investigate the potential role of glycosylated EMP3 in the mitochondria and how it could influence GBM independent of EMP3’s effects on EGFR." (PMID 37936247, 2023). "EMP1, EMP2, and EMP3 have been reported as novel therapeutic targets in human cancer." (PMID 36936167, 2023). "Expression analysis revealed a different mRNA expression pattern of EMPs with significant downregulation of EMP1 (nine out of ten cell lines) and EMP2 (six out of ten cell lines), but significant upregulation of EMP3 in more than half of the cancer cell lines compared to HBEC." (PMID 33799364, 2021). "Cancer stem cells are characterized by an increase in DNA damage repair capacity, therefore whether EMP3 modulates cancer cell stem-like properties were evaluated." (PMID 34511602, 2021). "However, recent findings suggested that the function of EMP3 in human cancers seems to be multi-facet." (PMID 27527869, 2017). "The clarification of the role of EMP3 may lead to a cure for malignant tumors." (PMID 34268874, 2021). "Considering that EMP1, EMP2, and EMP3 have been reported to play important roles in various malignant tumors, increased expression of EMP1 and EMP3, along with stromal cellularity and stromal atypia, imply that increased EMP expression in PT could suggest a higher malignant potential for PT." (PMID 32857809, 2020). "The apparently conflicting effects of EMP3 on proliferation of cancer cells in different tissues may simply reflect the different environments, both internal and external, that interact with the EMP3:CD44 membrane bound signalling complex." (PMID 32678083, 2020). "ALDH1 promotes the up-regulation of EMP3 in NSCLC cells and participates in the regulation of cell proliferation, anti radiation ability of cancer stem cells (CSCs) and epithelial mesenchymal transition (EMT) of NSCLC cells." (PMID 36217151, 2022). "Epithelial membrane protein 3 (EMP3), a member of the PMP22 gene family, is involved in human malignant tumors." (PMID 34511602, 2021).
EMP3 also shares sentences with these, for which no sentence is quoted: brain glioma (2 papers); uveal melanoma (2); breast tumor (1); colon cancer (1); endometriosis (1); epilepsy (1); head and neck squamous cell carcinoma (1); low grade glioma (1); oligoastrocytoma (1); prostate carcinoma (1); skin cancer (1); systemic lupus erythematosus (1); tumors of the nervous system (1); uterus cancer (1); viral myocarditis (1).